SLC1A5 (solute carrier family 1 member 5)
Diseases named in the same sentence as SLC1A5 in open-access papers (continued):
Sharing a sentence is not in itself a finding about the gene and the disease.
breast cancer (continued). "We generated co-expression networks according to the top-25 genes that highly interacted with SLC1A5 in both normal breast and breast cancer tissues." (PMID 34282517, 2021). "TNBC displays significantly increased SLC1A5-mediated glutamine uptake compared to luminal breast cancer cells." (PMID 32296646, 2020). "This study has also showed that YAP/TAZ expression positively correlates with GLS1 and SLC1A5 expression in human breast cancer patient samples." (PMID 32596154, 2020). "It has been revealed that EphA2 induces YAP/TAZ activation through RHOA activation, and activated YAP/TAZ promotes glutaminolysis through upregulation of GLS1 and SLC1A5 in HER2-positive breast cancer cells." (PMID 32596154, 2020). "For instance, targeting SLC1A5 inhibited cell proliferation in melanoma, prostate cancer, triple-negative basal-like breast cancer and gastric cancer." (PMID 31409775, 2019). "Triple-negative basal-like breast cancer cells had significantly higher SLC1A5-mediated glutamine uptake than luminal type cells." (PMID 29562706, 2018). "Paclitaxel-induced ER stress activates the ubiquitin ligase RNF5, resulting in ubiquitination and degradation of SLC1A5 and thereby reducing glutamine uptake in breast cancer cells." (PMID 29562706, 2018). "In breast cancer, glutamine is a key nutrient for cancer cell proliferation and survival, and it is largely regulated by amino acid transporters, especially SLC1A5 and SLC7A5." (PMID 29562706, 2018). "With regard to treatment resistance in breast cancer, SLC1A5 is involved in the treatment response to paclitaxel, a chemotherapy drug." (PMID 29562706, 2018). "In human breast cancer tissues, high SLC1A5 expression was observed in human epidermal growth factor receptor 2 (HER-2) type breast cancer by immunohistochemistry." (PMID 29562706, 2018). "Tamoxifen and raloxifene, two selective estrogen receptor (ER) modulators, suppress SLC1A5 expression and thereby inhibit SLC1A5-mediated glutamine uptake and proliferation of ER-negative breast cancer cells." (PMID 29562706, 2018). "Considerable evidences supported that SLC1A5 was highly expressed in numbers of human malignant tumors, such as breast cancer, prostate cancer, lung cancer, esophageal squamous cell carcinoma, laryngeal squamous cell carcinoma, tongue cancer and melanoma, etc." (PMID 29100325, 2017). "Geldermalsen reported that SLC1A5 is highly expressed in triple-negative basal-like breast cancer, and promotes cell proliferation in vitro and in vivo." (PMID 29100325, 2017). "Additionally, we demonstrate that serine provided by ASCT2 is critical for purine nucleotide biosynthesis and characterize a mechanism of SLC1A5 regulation by estrogen receptor α (ERα) in ER+ breast cancer." (PMID 39068660, 2024). "Also, curcumin exerts anticancer activity against breast cancer cells by promoting SLC1A5-mediated ferroptosis." (PMID 38705513, 2024). "circ_0062558 could enhance glutamine transport through the miR-876-3p/SLC1A5 axis to support the energy requirements for breast cancer development." (PMID 38408962, 2024). "Moreover, SPOP and SLC1A5 levels are inversely associated in human breast cancer specimens, and lower SPOP and higher ASCT2 levels predict poorer patient survival." (PMID 37190313, 2023). "SLC1A5 is highly expressed in breast cancer, liver cancer, CRC, and other cancers." (PMID 37190313, 2023). "This regulates the stability of SLC1A5 protein, thereby reducing the uptake of glutamine by cells, inhibiting the mechanistic target of rapamycin (mTOR)-signaling pathway and reducing the growth rate of breast cancer cells." (PMID 37190313, 2023). "In breast cancer, curcumin suppressed tumorigenesis via enhancing SLC1A5-mediated ferroptosis." (PMID 36838613, 2023).
breast cancer (continued). "In addition, miR-107, miR-149-5p, and miR-924 were shown to regulate SLC1A5 in esophageal cancer, breast cancer, and non-small-cell lung cancer cells respectively; however, they were sponged by circular RNA to prevent downregulation of SLC1A5." (PMID 35755805, 2022). "Interestingly, a recent study showed that inhibition of SLC1A5/ASCT2 significantly reduced glutamine uptake in a human breast cancer cell line in a subtype‐dependent manner, with suppression of mTOR signaling, cell growth, and cell cycle progression." (PMID 34003553, 2021). "A recent In vitro study demonstrated that SLC1A5 is upregulated in breast cancer cells resistant to endocrine therapy and that SLC1A5 inhibition decreased cell proliferation in aromatase inhibitors resistant breast cancer cells." (PMID 34282517, 2021). "Therefore, in this study, we investigated the prognostic role of SLC1A5 in luminal breast cancer and determined the effect of SLC1A5 silencing as to the sensitivity of endocrine treatment." (PMID 34282517, 2021). "Slc1a5 shows an expression pattern similar to that of Slc38a1; it is expressed at low levels in normal mammary tissue and it is up-regulated in all three subclasses of breast cancer." (PMID 34704597, 2021). "On basis of the network analysis and positive correlation of TALDO1 with SLC1A5 in luminal breast cancer, we performed further analysis with a focus on the potential clinical role of TALDO1 in luminal breast cancer and prediction of benefit from endocrine treatment." (PMID 34282517, 2021). "Consistent with our clinical findings, SLC1A5 knockdown resulted in increased sensitivity to tamoxifen in luminal breast cancer cells, suggesting that high SLC1A5 expression might play a crucial role in therapeutic response to endocrine treatment." (PMID 34282517, 2021). "In breast cancer, SLC1A5 expression varies based on the molecular subtype." (PMID 29562706, 2018). "Conversely, SLC1A5 upregulation in breast cancer cells decreases paclitaxel responsiveness." (PMID 29562706, 2018). "In breast cancer, SLC1A5 and SLC6A14 are upregulated amino acid transporters that carry glutamines, and therefore glutamine metabolism may largely affect tumor biology." (PMID 29562706, 2018). "Glutamine transport is largely mediated by alanine, serine, cysteine-preferring transporter 2 (ASCT2; SLC1A5) in multiple cancers, including melanoma, non-small cell lung cancer, prostate cancer, acute myeloid leukaemia, multiple myeloma, and breast cancer." (PMID 29940911, 2018). "However, silencing certain SLC genes (e.g., SLC1A5 in breast cancer and SLC6A14 in colorectal cancer) can significantly impair L‐serine uptake, leading to metabolic disruption, as compensatory changes in other SLCs fail to sustain intracellular L‐serine levels." (PMID 40971730, 2025). "Patients with high SLC1A5 expression experienced poorer outcomes following endocrine therapy, while the co-expression of SLC1A5 and TALDO1 was significantly associated with a higher risk of recurrence and mortality in breast cancer patients receiving endocrine therapy." (PMID 41154605, 2025). "Patients with SLC1A5 + TALDO1 + had the worst outcome and further analysis revealed a significant association between SLC1A5 + TALDO1 + expression and a high risk of recurrence and death from breast cancer in patients who had received adjuvant endocrine therapy only." (PMID 34282517, 2021). "In conclusion, our findings suggested that the contribution of SLC1A5 expression in luminal breast cancer and failure of endocrine treatment might be through participation in the pentose phosphate pathway via regulation of TALDO1 expression essential for cancer cells growth and proliferation." (PMID 34282517, 2021). "Additionally, patients with luminal breast cancer could be classified either as having a good or poor response to endocrine therapy according to SLC1A5/TALDO1 co-expression." (PMID 34282517, 2021).
breast cancer (continued). "Furthermore, univariate and multivariate analysis of individual protein expression profiles demonstrated the central role of serine hydroxymethyltransferase 2 (SHMT2) and amino acid transporter ASCT2 (SLC1A5) as independent prognostic factors in breast cancer patients." (PMID 29020998, 2017). "It has been demonstrated that SLC1A5, SLC6A14, SLC7A11, SLC3A1, SLC7A5, SLC38A2, and SLC38A5 are significantly expressed in breast cancer cells." (PMID 39973065, 2025). "When treated with the SLC1A5 inhibitor L-γ-glutamyl-p-nitroanilide (GPNA), different molecular subtypes of breast cancer cells, including luminal, basal-like, and claudin-low, showed significant inhibition of glutamine uptake." (PMID 39973065, 2025). "Key transporters, such as SLC1A5 (also known as ASCT2) and SLC7A5 (LAT1), facilitate glutamine and essential amino acid uptake, respectively, and are upregulated in various breast cancer subtypes." (PMID 39973065, 2025). "Analyzing pathways involving amino acid transporters (e.g., SLC1A5) or enzymes (e.g., GLS) can guide the use of glutaminase inhibitors, such as CB-839, for glutamine-addicted breast cancer." (PMID 39973065, 2025). "The increased activity of transmembrane transporters SLC1A5 and SLC38A2 was shown in TNBC and HER2-positive breast cancer." (PMID 39852119, 2024). "In drug-resistant breast cancer MYC is overexpressed, glutamine transporter proteins SLC1A5 and GLS are upregulated, and glutamate metabolism is markedly enhanced to promote proliferation of drug-resistant tumor cells." (PMID 39027328, 2024). "Besides, under hypoxia, Bca cells also depended on glutamine required for cell growth, and pharmacological inhibition of HIF-regulated SLC1A5 using V-9302 could block breast cancer cell growth, along with decreased mTOR signaling and increased ROS levels and autophagy." (PMID 36967443, 2023). "Dual targeting of SLC6A14 with SLC25A15, SLC12A4, SLC1A5 and SLC38A5 also reduced growth in MCF7 and MDA-MB-231 human breast cancer cell lines." (PMID 38066114, 2023). "In breast cancer, RNF5 is involved in the degradation of glutamine transporters SLC1A5 and SLC38A2, which are aberrantly folded following chemotherapy-induced ER stress." (PMID 35406574, 2022). "AI-resistant breast cancer cells show significant upregulation of the glutamine transporters SLC1A5 and GLS, and inhibition of MYC, SLC1A5, and GLS decrease cell proliferation in AI-resistant cells." (PMID 36059650, 2022). "In this study, we used isotopically labelled glutamine to resolve glutamine utilisation in two different breast cancer subtypes (TNBC vs. Luminal A), with the TNBC subtypes sensitive to inhibition of SLC1A5/ASCT2-mediated glutamine uptake." (PMID 35851845, 2022). "Inhibition of glutamine uptake by an antagonist of the amino acid transporter ASCT2 (SLC1A5) promotes B7/H3 degradation through autophagy and ROS production in breast cancer cell lines, favoring the activation of tumor-infiltrating CTLs." (PMID 36713558, 2022). "In contrast to RNF5 pro-tumor activity, in breast cancer, RNF5 promoted ubiquitination and degradation of glutamine transporters SLC1A5 and SLC38A2, which were aberrantly folded following chemotherapy-induced ER stress." (PMID 35406574, 2022). "We next investigated the correlation between the mRNA expression of SLC1A5 and TALDO1 and proliferation-related genes in patients with luminal breast cancer using METABRIC cohort." (PMID 34282517, 2021). "Taken together, the combined expression of SLC1A5 and TALDO1 has a utility value as a prognostic marker of poor clinical outcome in luminal breast cancer." (PMID 34282517, 2021). "This study demonstrated the prognostic value of both SLC1A5 and TALDO1 as biomarkers in luminal breast cancer." (PMID 34282517, 2021).
breast cancer (continued). "As our results demonstrated the prognostic value of SLC1A5 and TALDO1 singularly in luminal breast cancer, we also established the co-expression impact of these markers on the clinical outcome and efficacy of adjuvant endocrine treatment." (PMID 34282517, 2021). "Here, we found a prognostic utility of the amino acid transporter SLC1A5 and the metabolic enzyme TALDO1 in luminal breast cancer and endocrine therapy." (PMID 34282517, 2021). "In aromatase inhibitor-resistant breast cancer, overexpression of the oncogene MYC upregulates SLC1A5 expression via crosstalk between ER and HER-2." (PMID 29562706, 2018). "QPCR analysis performed at two different time points, 48h and 72h, indicated an up-regulation of Slc1a5, GOT1 and IDH1 at 72h in FSK treated samples, hence confirming also in human breast cancer cells a role of PKA activation in glutamine metabolism." (PMID 26978032, 2016). "RNF5 regulates the turnover of SLC1A5 and SLC38A2 in about 30% of breast cancer patients that are responsive to taxanes-based therapies, which is associated with better prognosis." (PMID 26425657, 2015). "Therefore, SLC1A5 and TALDO1 can be used to predict the prognosis of endocrine therapy in luminal breast cancer." (PMID 39973065, 2025). "SLC1A5, SLC3A2, SLC7A5, and SLC6A14 may be promising biomarkers for BC [breast cancer] diagnosis and may represent potential therapeutic targets for these patients”." (PMID 37627015, 2023). "SLC1A5 plays a role in lung cancer and SLC7A8 is involved in breast cancer development." (PMID 35565312, 2022). "The expression of SLC1A5 was mainly observed in the membrane of the invasive breast cancer cells, with expression levels varying from negative to high." (PMID 34282517, 2021). "Some amino acid transporters, including SLC1A5, SLC6A14, SLC7A5, and SLC7A11, may be promising targets for the treatment of breast cancer since they modulate tumor growth, metastasis, treatment response, and prognosis of breast cancer." (PMID 29562706, 2018). "As the active form of vitamin D, 1,25-dihydroxyvitamin D (1,25(OH)2D) downregulates SLC1A5 and reduces glutamine uptake and utilization in Harvey-ras oncogene-transformed MCF10A human breast epithelial cells, potentially contributing to breast cancer prevention." (PMID 29562706, 2018). "In previous studies, mice with deficiencies in SLC1A5, SLC6A14, and SLC7A11, which have been reported to be upregulated in breast cancer, were found to be viable and fertile and to have no abnormal phenotypes." (PMID 29562706, 2018). "Overall, the level of the glutamine carrier proteins SLC1A5 and SLC38A2 was found to be excellent predictor of the outcome for breast cancer patients where a low level of these carrier proteins associates with a better outcome, including a better response to therapy." (PMID 26425657, 2015). "According to the type of breast cancer (i.e., HER2+ or ER+), several amino acid transporters, such as SLC1A5, SLC6A14 and SLC7A5, were shown to have different expressions in BC tissue compared to controls." (PMID 37628869, 2023). "Additionally, we suggest that SLC1A5 is a potential therapeutic target for overcoming endocrine resistance and demonstrates the prognostic value of both SLC1A5 and TALDO1 as biomarkers for predicting endocrine therapy guide in luminal breast cancer." (PMID 34282517, 2021). "However, no previous study has reported utility of SLC1A5 in predicting the benefit of endocrine therapy in luminal breast cancer." (PMID 34282517, 2021). "Interestingly, although glutamine metabolism is independent of estrogen in aromatase inhibitor-resistant breast cancer, the cross-talk between ER and HER2 upregulates the c-MYC pathway and further increases the expression level of GLS, SLC1A5, and glutamine consumption." (PMID 36077501, 2022).
melanoma (63 papers, 2015 to 2025). A malignant, usually aggressive tumor composed of atypical, neoplastic melanocytes. "Reduced SLC1A5 expression has been linked to increased ferroptosis, decreased glutamine synthesis, and decreased glutamine accumulation in melanoma." (PMID 37996827, 2023). "Going further, miR‐let7a can directly or indirectly regulate the expression of key genes in the ferroptosis process, such as targeting glutamine transporter SLC1A5 to modulate ferroptosis in melanoma cells." (PMID 40237277, 2025). "Experiment have shown that miR-137 inhibits melanoma cells’ ferroptosis by targeting SLC1A5, leading to a decrease in Gln uptake and malondialdehyde (MDA) accumulation." (PMID 38388534, 2024). "Emerging studies in melanoma cells showed that miR-137 inhibited lipid peroxidation and iron accumulation by directly targeting solute carrier family 1 member 5 (SLC1A5)." (PMID 38392340, 2024). "In contrast, in melanoma patients from the Nathanson_2017 cohort, it was observed that patients with low expression of SLC1A5 who received ai_CTLA-4 treatment had a worse prognosis." (PMID 37566748, 2023). "By focusing on the control of the glutamine transporter SLC1A5 as a novel therapeutic target for melanoma, miR-137 can inhibit ferroptosis in melanoma cells." (PMID 37240889, 2023). "In melanoma patients, it was observed that low expression levels of SLC1A5 in the GSE78220_anti-PD1 and GSE106128_DCs cohorts were significantly associated with a favorable response to ICB therapy." (PMID 37566748, 2023). "For example, overexpression of miR-137 in melanoma cells downregulated the expression of glutamine transporter SLC1A5, reduced the process of lipid peroxidation, and the accumulation of iron, which reduced ferroptosis." (PMID 37996827, 2023). "MiR-137 has been shown to directly bind to SLC1A5 in melanoma, which suppresses ferroptosis through the downregulation of SLC1A5." (PMID 35755805, 2022). "SLC1A5 was found highly expressed also in melanoma cells where it promoted cell proliferation and resistance to conventional therapies." (PMID 35406574, 2022). "Accordingly, pharmacologically and genetic inhibitions of SLC1A5 led to regression of cell proliferation and were proposed as a potential therapeutic target for melanoma." (PMID 35406574, 2022). "In melanoma, miR-137 can negatively regulate ferroptosis by targeting SLC1A5 to promote cancer progression." (PMID 35419359, 2022). "It has been shown in melanoma cells that miR-137 inhibits lipid peroxidation and iron accumulation in vitro and in vivo by directly targeting solute carrier family 1 member 5 (SLC1A5)." (PMID 35422492, 2022). "By directly targeting the glutamine transporter SLC1A5, miR-137 negatively regulates ferroptosis in melanoma cells and is considered a potential therapeutic approach for melanoma." (PMID 36081847, 2022). "SLC1A5 is a target of miR-137 and is expressed at elevated levels in melanoma, neuroblastoma, and prostate cancer." (PMID 35305616, 2022). "Previous research has shown that miR-137 suppresses ferroptosis by targeting the glutamine transporter SLC1A5 and decreases the antitumor activity of erastin in melanoma." (PMID 34708125, 2021). "For example, the SLC1A5 inhibitor benzylserine (Benser) hampers the proliferation of tumor cells in human gastric cancers and in melanoma cell lines." (PMID 33505538, 2021). "Melanoma is a kind of skin tumor with high malignant degree, and miR-137 can mediate the glutamine transporter SLC1A5 to regulate the occurrence of ferroptosis in melanoma cells." (PMID 34413966, 2021). "Overexpression of SLC1A5 can attenuate ferroptosis suppression mediated by miR-137 in melanoma cells." (PMID 33727924, 2021). "In a study of melanoma, it was found that miR-137 negatively regulates ferroptosis by directly acting on the glutamine transporter SLC1A5 in melanoma cells, while knockdown of miR-137 promotes ferroptosis." (PMID 32015325, 2020).